EGFR (epidermal growth factor receptor)
Diseases named in the same sentence as EGFR in open-access papers (continued):
Sharing a sentence is not in itself a finding about the gene and the disease.
lung cancer (continued). "Key elements of the MAPK pathway, such as EGFR, RAS, ERK, and MET, are recognized lung cancer therapeutic targets." (PMID 41019373, 2025). "In lung cancer, ADAMTS8 enhances survival, especially in patients with wild-type EGFR or low PD-L1 expression, by promoting anti-cancer NKT cells and reducing immunosuppressive T cells." (PMID 40650042, 2025). "After the validation of the optimized molar ratios in GM‐protac, we then evaluate the EGFR degradation activity and HDAC inhibition effect on different lung cancers." (PMID 40842076, 2025). "A specific flavonoid glycoside modulates integrin β1, EGFR, COX-2, MMPs, EMT markers, and STAT3/NF-κB/PI3K pathways in lung cancer." (PMID 41346617, 2025). "These agents offer novel therapeutic options with the potential to overcome resistance to third-generation EGFR-TKIs in NSCLC and other lung cancers." (PMID 40277759, 2025). "Gefitinib was the first TKI of EGFR to receive the United States Food and Drug Administration (USFDA)’s approval for the treatment of lung cancer in 2015." (PMID 40940888, 2025). "In two canine studies, EGFR and VEGFR2 were shown to be expressed in canine lung carcinomas, but their prognostic significance is unclear." (PMID 40969344, 2025). "First, immunohistochemical interrogation of 89 EGFR-mutant, 51 KRAS-altered, and 46 ALK-rearranged lung cancer specimens unveiled that YY1 was ubiquitously expressed in malignant cells at an elevated level relative to the normal epithelium." (PMID 39604408, 2024). "On the other hand, inhibition of STAT3 abrogates erlotinib resistance in lung cancer cells, suggesting a feedback loop between STAT3 and EGFR." (PMID 39967270, 2024). "Among those aged ≥40 years, who accounted for 88.4% of the total number of people with disabilities, the top three most frequently used tests were colorectal and lung cancer‐related (KRAS, NRAS, and EGFR)." (PMID 38711356, 2024). "Gefitinib, a first-generation epidermal growth factor receptor-tyrosine kinase inhibitor (EGFR-TKI), is commonly used as a first-line treatment for EGFR-mutant lung cancers due to its effectiveness in the initial treatment phase." (PMID 39735556, 2024). "This study focuses on CTX‐1, exploring its interaction with the pivotal EGFR‐TKD protein, a crucial target in lung cancer therapeutics." (PMID 38685671, 2024). "This activation mechanism of variant type 1 has been reported, and several cases are successful against EGFR TKI, including in lung cancer and colorectal cancer." (PMID 39054543, 2024). "We then encapsulated the engineered exosomes armed to EGFR with LPCAT1 siRNA (siLPCAT1) and intravenously injected them into a mouse model of lung cancer BM." (PMID 38589859, 2024). "In conclusion, ALK‐positive lung cancer patients exhibit higher CYFRA21‐1 positivity and have higher CYFRA21‐1:CEA ratios compared with EGFR‐positive lung cancer patients." (PMID 38400801, 2024). "We employed the lightweight CNN model to classify patient-derived lung cancer cells, both categorized as adenocarcinomas but with distinct genetic profiles: one harboring the KRAS oncogene (HCC 4087) and the other the EGFR oncogene (HCC 4190)." (PMID 39180048, 2024). "Finally, we delved into the EGFR downstream signaling pathway and observed that several EGFR signaling-related proteins such as p-AKT, p-STAT3, JNK, and p-ERK were decreased upon GLUT1 knockdown, suggesting GLUT1 could activate EGFR signaling pathway in lung cancer." (PMID 38831321, 2024). "EGFR, ALK, VEGF, and KRAS are the most important signaling pathways which have been identified and are involved in the progression of lung cancer." (PMID 38234663, 2024). "Starting in 2010, the epidermal growth factor receptor (EGFR) kinase inhibitor drugs erlotinib and gefitinib were introduced into routine clinical use in NZ for the treatment of advanced lung cancer." (PMID 38954434, 2024). "A large number of studies on lung cancer mainly focused on AKT/mTOR/NF-κB, EGFR-AKT-mTOR, and PI3K/ AKT/mTOR signal pathways." (PMID 38571356, 2024).
lung cancer (continued). "In lung cancer, β1 integrin–SRC–AKT is suggested to play a central role in acquired resistance to EGFR-targeted drugs." (PMID 39769452, 2024). "The engineering of CCR6, the receptor for CCL20, within epidermal growth factor receptor (EGFR)-targeting CAR-T cells led to improved trafficking, penetration, and clearance of solid tumors in a CCL20+ lung cancer xenograft mouse model." (PMID 38217016, 2024). "Targeting specific proteins such as SRC, STAT3, PIK3CA, MAPK1, EGFR, and JAK1 is crucial for impeding the growth of lung cancer." (PMID 38921583, 2024). "In our case, the patient exhibited a notable clinical improvement primarily due to the administration of almonertinib, a third-generation EGFR-TKI, which underscores the potential efficacy of targeted therapy in managing ARDS secondary to advanced lung cancer." (PMID 39334060, 2024). "The EGF receptor (EGFR) family consists of four transmembrane receptors, which include EGFR (HER1/erbB-1), HER2 (erbB-2/neu), HER3 (erbB-3), and HER4 (erbB-4); and is commonly overexpressed in lung cancer." (PMID 39218855, 2024). "However, some studies have suggested that dysregulation of the Wnt pathway may be an important factor contributing to enhanced maintenance and proliferation signaling in various cancers, and crosstalk between EGFR and the Wnt signal pathway may enhance lung cancer tumorigenesis." (PMID 39551860, 2024). "In lung cancer, FBXW2 can inhibit the proliferation and metastasis of lung cancer by activating EGFR signaling pathway." (PMID 39075515, 2024). "In a separate study, the overexpression of EGFR in lung cancer cell membranes has been shown to stabilize the SCD1 protein, leading to an increase in intracellular MUFAs and promoting lung cancer growth." (PMID 39658456, 2024). "This combined approach emerges as a promising strategy to tackle EGFR-TKI resistance and sensitize lung cancer cells, providing a comprehensive solution to navigate the intricacies of oncogenic signaling and cellular defense mechanisms." (PMID 39104501, 2024). "We also performed GSEA analysis to further explore the mechanisms of PHF12 in lung cancer development, and the results also showed that PHF12 was related to EGFR/ErbB2 signaling pathway." (PMID 39075515, 2024). "There is ongoing research to identify biomarkers that can predict response to either EGFR-TKI therapy and to immune therapy in lung cancer, including gene expression profiling and analysis of immune cell populations within the tumor microenvironment." (PMID 39034310, 2024). "Gefitinib, the first-generation EGFR-TKI, has greatly improved survival rates in lung cancer patients, whereas acquired gefitinib resistance is still a critical issue that needs to be overcome." (PMID 39264588, 2024). "The application of EGFR‐TKI has been reported to alleviate abnormal coagulation, leading to longer OS in progressive lung cancer." (PMID 39021279, 2024). "In a recent study, a label-free electrochemical biosensing system was developed for the sensitive detection of epidermal growth factor receptor (EGFR), a protein frequently overexpressed in various cancers, including lung cancer, breast cancer, and GBM." (PMID 38732975, 2024). "Epalrestat restored the chemosensitivity of lung cancer cells resistant to epidermal growth factor receptor (EGFR), and tyrosine kinase inhibitor (TKI), in addition to delaying resistance in a murine lung cancer xenograft model." (PMID 39055885, 2024). "In our comprehensive study, we conducted molecular modelling analyses to identify potential drug candidates for targeting four key proteins involved in lung cancer: CDK2, SRC-2 domains of C-ABL, EGFR, and IGF-1R kinase." (PMID 38905286, 2024). "In lung cancer cell lines, the reciprocal interaction between BASP1 and EGFR was found to facilitate EGFR signaling in brain-metastatic lung cancer." (PMID 38464823, 2024).
lung cancer (continued). "EGFR, MSLN, MUC1, CEA, PD-L1, ROR1, HHLA2 (also referred to as B7H7), HER2, and various other target antigens are being studied for CAR-T therapy in lung cancer." (PMID 38622705, 2024). "In EGFR-positive lung cancer, upregulation of G9a, through silencing of miR-145-5p, promotes HER3 expression, facilitating EGFR-TKI resistance." (PMID 38525426, 2024). "Initially, lentiviral CRISPR-Cas9 technology was employed to knockout YY1 in multiple EGFR-mutant, KRAS-altered, or ALK-rearranged lung cancer cell lines using two independent sgRNAs, and cell viability was significantly inhibited without exception." (PMID 39604408, 2024). "Our study provides, for the first time, insights into the real‐world utilization of EGFR, ALK, and BRAF inhibitors in the therapy of lung cancer patients in Germany." (PMID 39693368, 2024). "The current study demonstrates the success of a combinatorial therapeutic approach with PPL and EGFR-TKIs (GEF and ERL) to overcome resistance and enhance the anticancer effect of lung cancer cells." (PMID 39449797, 2024). "AREG, in turn, upregulates the glutamine transporter SLC1A5 and promotes the accumulation of glutamine-derived TCA cycle metabolites via the EGFR/PI3K/AKT/mTOR signaling pathway, thereby promoting lung cancer cell growth and proliferation." (PMID 38904011, 2024). "In lung cancer cells, DRD1 signaling reduces proliferation through reduced EGFR signaling, and it also reduces PD‐L1 expression." (PMID 38572507, 2024). "Recently, CD200 has been proposed as a marker for CAFs in lung cancer, and it has been shown that high expression of CD200 in CAFs increases their sensitivity to EGFR/TKI inhibitors, such as Gefitinib, and induces cancer cell apoptosis." (PMID 39403603, 2024). "For example, the interaction of EpEX with EGFR was previously reported to activate AKT and ERK1/2 pathways, promoting tumor progression in both lung cancer and CRC models." (PMID 39010070, 2024). "Combination treatments for lung cancer, such as bevacizumab, a monoclonal antibody that targets VEGF, and erlotinib, an EGFR inhibitor, can extend the PFS in patients with NSCLC." (PMID 38785748, 2024). "Using an EGFR L858R/T790M transgenic mouse model, K-K Wong’s team showed that second-generation EGFR TKI afatinib (BIBW2992) induced tumor regression in xenograft and transgenic lung cancer models." (PMID 39796653, 2024). "In patients with no smoking history, EGFR mutations may be more of a driver of lung cancer." (PMID 39634906, 2024). "Although we focus on oncogenic EGFR-driven lung adenocarcinomas, our findings appear to extend to other molecular subsets such as EML4-ALK-driven lung cancer and likely reflect a more general principle of targeted therapy-induced adaptability." (PMID 38049664, 2024). "Anaplastic lymphoma kinase (ALK), epidermal growth factor receptor (EGFR), ROS proto-oncogene 1 (ROS1), and serine/threonine-protein kinase B-Raf (BRAF) inhibitors have become key components of lung cancer therapy." (PMID 38785748, 2024). "Lapatinib is a dual epidermal growth factor receptor (EGFR)/HER2 inhibitor approved for use in HER2+ BC, while erlotinib and gefitinib target EGFR and are used to treat lung cancer." (PMID 39280248, 2024). "In the study of lung cancer proteomics, proteins in receptor tyrosine kinases such as EGFR and ALK and their downstream signalling pathways play a key role in the pathological process of lung cancer." (PMID 39391313, 2024). "Erlotinib, another selective EGFR-TKI, increase the ROS levels in lung cancer cells, promoting JNK phosphorylation that activates c-Jun and caspase-3 to lead to apoptosis." (PMID 38982494, 2024). "This inhibitory effect is attributed to the modulation of oncogenic signaling pathways related to EGFR and FGER in lung cancer." (PMID 38398785, 2024). "The roles of lung cancer-related genes, such as KRAS, EGFR, and ALK, have been systematically investigated in specific animal models of cancers." (PMID 39311119, 2024).
lung cancer (continued). "Alterations in the epidermal growth factor receptor (EGFR) serve as crucial indicators for the detection and management of lung cancer, particularly NSCLC." (PMID 39464709, 2024). "Our previous publication documented that EGFR and c-MET are upstream molecules of the PI3K/Akt pathway in B[α]P and CSE-regulated lung cancer chemoresistance." (PMID 38993553, 2024). "Initially developed for lung cancer, IRESSA is an epidermal growth factor receptor (EGFR) tyrosine kinase inhibitor." (PMID 38399423, 2024). "In total, 66 samples obtained from 30 patients with lung cancer pre-TKI or post-TKI therapy (erlotinib (EGFR), osimertinib (EGFR) and crizotinib (ALK) being the most frequent targeted therapies) were analyzed." (PMID 38049664, 2024). "In MET-amplified NSCLC, heterodimers of MET with EGFR, HER2, and HER3 activate the AKT and ERK signaling pathways, thereby enhancing lung cancer cell proliferation and survival." (PMID 39201787, 2024). "In our study, we confirmed for the first time the promoter role of PHF12 in non-small cell lung cancer and proposed that PHF12-HDAC1 axis regulates the EGFR/AKT signaling pathway and promotes the development of lung cancer." (PMID 39075515, 2024). "In lung cancer, PTPN3 has been shown to limit cellular proliferation and invasion by increasing EGFR endocytic degradation." (PMID 38173048, 2024). "If a patient has EGFR-driven NSCLC, they are in some ways fortunate because this is the most common type of lung cancer, and it has been studied extensively." (PMID 38497774, 2024). "Globally, the majority of cancer-related deaths are attributed to lung cancer, with around 50% of Asian individuals diagnosed with NSCLC showing variations in the EGFR." (PMID 38794196, 2024). "EGFR-TKIs, including erlotinib and gefitinib, can induce plasma membrane-associated EGFR protein degradation, and the inhibition of STAT3 abrogates erlotinib resistance in lung cancer cells, suggesting that a high level of plasma membrane-associated EGFR may be important in EGFR-TKI resistance." (PMID 39967270, 2024). "Epidermal growth factor receptor (EGFR) tyrosine kinase inhibitors such as gefitinib and erlotinib are typically the first chemotherapy treatments for lung cancer." (PMID 38398785, 2024). "Lung cancer is the most commonly occurring cancer globally with NSCLC accounting for the vast majority of cases and EGFR being one of the main driver genes." (PMID 39202551, 2024). "EGFR, another member of the ErbB family, is upregulated in glioblastoma multiforme, breast, colorectum (CRC), and lung carcinomas." (PMID 38545115, 2024). "We calculated the half inhibitory concentration (IC50) of DDD85646 on EGFR mutant (H1975 and H1650) and KRAS/EGFR wild-type lung carcinoma cells (H1299 and H522) at 72 hours of treatment." (PMID 38949950, 2024). "Another mutation in a different gene is PIK3CA, which drives resistance to EGFR-TKIs by activating bypass AKT signaling; it is found in 4% of patients with lung cancers and in 3.5% of EGFR mutant NSCLC." (PMID 37240224, 2023). "Better inhibition of EGFR-mutant lung cancer cells was observed with the combination of EGFR and PLK1 inhibitors compared to EGFR inhibition alone." (PMID 37174055, 2023). "We investigated the possibility of the spike 1 S protein and its receptor-binding domain (RBD) to target the epidermal growth factor receptor (EGFR) and its downstream signaling pathway in vitro using the lung cancer cell line (A549 cells)." (PMID 37112680, 2023). "For instance, the epidermal growth factor receptor (EGFR) was introduced on exosomal surfaces for reinforced targetability, considering that lung cancer is EGFR-positive." (PMID 37635253, 2023). "Through detailed EGFR-TKI response analysis, we showed that the PDC molecular subtype uncovers the clinical characteristics and resistance factors of lung cancer patients." (PMID 36717865, 2023).
lung cancer (continued). "Building upon this knowledge, we screened for dysregulated circRNAs in Osimertinib-resistant lung cancer groups and investigated the suppressed circ-FBXW7's role in controlling the functional EGFR pathway." (PMID 37393311, 2023). "Collectively, the small-molecular agonist JAC4 of the JWA gene inhibited EGFR-driven lung-cancer growth and metastasis via the AMPK-NEDD4L-EGFR axis." (PMID 37240137, 2023). "On the other hand, a study performed in NSCLC reported that the functional expression of SCN9A (Nav1.7) is controlled by EGF/EGFR signaling through the ERK1/2 pathway, which in turn promotes the invasion of H460 lung cancer cells." (PMID 37408210, 2023). "In this study, through systematic screening analyses, we report that LAMC2 is an EGFR TKI sensitive gene with both oncogenic and protein transport functions in lung cancer." (PMID 37542131, 2023). "Genistein was also reported to inhibit NF-κB DNA-binding affinity and downregulate expression of COX-2, p-Akt, EGFR, and PGE2, resulting in decreased cell proliferation and upregulation of apoptosis in H3255, H1650, and H1781 lung cancer cell lines." (PMID 37568796, 2023). "The cytotoxic effects of PM2.5 on normal lung and lung cancer cells were evaluated by short‐term 24‐h exposure using the normal lung fibroblast cell lines MRC5 and IMR90 and lung cancer cell lines A549 (EGFR wild‐type) and H1975 (EGFR L858R+T790M)." (PMID 36975376, 2023). "Many studies have shown that, as important genes constituting the ERBB network, EGFR and ERBB2 (20ins) are significantly related to the development and invasion of lung cancer." (PMID 36816028, 2023). "Corroborating previous findings in other cancer cell lines, our results indicated that LAMC2 expression promoted the phosphorylation of EGFR, as well as its downstream targets AKT and ERK1/2 in A549, NCI-H23, and HCC827 lung cancer cells." (PMID 37542131, 2023). "In preclinical lung cancer tumor models, inhibition of DYRK1A results in decreased STAT3/EGFR/Met signaling and NSCLC sensitization to EGFR inhibitor AZD9291 (Li YL." (PMID 37900285, 2023). "Current antigen targets in clinical trials for CAR-T cell therapy for lung cancer include MUC-1, CEA, HER2, mesothelin, receptor tyrosine kinase-like orphan receptor 1 (ROR1), glypican-3 (GPC3), EGFR, and PD-1." (PMID 37420216, 2023). "One major role for liquid biopsy in managing lung cancer metastasis is in the context of leptomeningeal metastasis (LM), which occurs in approximately 3–5% of NSCLC and is more common in EGFR-mutant NSCLC." (PMID 37240238, 2023). "As a result, the current investigation indicated that the described thiazolyl pyridines are promising EGFR inhibitors and pave the way for the synthesis of other libraries based on the reported scaffold, which may eventually result in the creation of an effective therapy for lung cancer." (PMID 37298747, 2023). "Similar to the function in lung cancer cells, TSPAN6 binds to the EGFR and blocks EGFR-induced RAS activation, thus inhibiting EMT process and cell migration." (PMID 36941633, 2023). "This study provides new insights regarding tumor evolution due to EGFR signaling after lorlatinib treatment and the development of combined therapeutic strategies for ALK-rearranged lung cancer." (PMID 36702855, 2023). "Other EGFR‐LFD cases included five cases of colorectal cancer, three cases of lung cancer, and one case of cholangiocarcinoma and melanoma." (PMID 36622089, 2023). "We established gefitinib-resistant cells (PC9/GR and HCC827/GR) by exposing EGFR-mutant PC9 and HCC827 human lung cancer cells to increasing concentrations of gefitinib." (PMID 36760347, 2023).